ALDOC (aldolase, fructose-bisphosphate C)
Description:
Catalyzes the reversible conversion of beta-D-fructose 1,6-bisphosphate (FBP) into two triose phosphate and plays a key role in glycolysis and gluconeogenesis.
Synonyms: ALDC
Tractability: Small molecule: it has a high-quality binding pocket. Antibody: its Gene Ontology location is reachable by antibodies, with high confidence. PROTAC: ubiquitination databases record sites on it; its protein half-life has been measured.
Target class: Enzyme; Lyase
Gene: Protein-coding gene on chromosome 17 (28,573,115 to 28,576,948, reverse strand). Ensembl gene ENSG00000109107.
Subcellular location (Human Protein Atlas): Nucleoli fibrillar center; Nucleoplasm; Cytosol; Vesicles
Pathways (Reactome):
Metabolism: Gluconeogenesis; Glycolysis
Immune System: Neutrophil degranulation
Gene Ontology:
Molecular function: cytoskeletal protein binding; fructose-bisphosphate aldolase activity; protein binding
Biological process: epithelial cell differentiation; fructose 1,6-bisphosphate metabolic process; canonical glycolysis; fructose metabolic process; gluconeogenesis; glycolytic process
Cellular component: extracellular exosome; cytoskeleton; cytosol; extracellular region; ficolin-1-rich granule lumen; secretory granule lumen; tertiary granule lumen
Genetic constraint (gnomAD): Loss-of-function variants: 23 observed, 41.51 expected, observed/expected ratio (o/e) 0.55, 90% interval 0.4 to 0.79. The upper end of that interval is the gene's LOEUF score, 0.79, which puts it in group 3 of 6, group 1 being the genes least tolerant of losing a copy. Missense variants: 356 observed, 499.28 expected, observed/expected ratio (o/e) 0.71, 90% interval 0.65 to 0.78. Synonymous variants: 160 observed, 191.08 expected, observed/expected ratio (o/e) 0.84, 90% interval 0.74 to 0.95.
Homologues: Orthologues: chimpanzee ALDOC (99% identical), macaque ALDOC (99% identical), rabbit ALDOC (99% identical), dog ALDOC (99% identical), pig ALDOC (99% identical), guinea pig ALDOC (98% identical), mouse Aldoc (98% identical), rat Aldoc (97% identical), tropical clawed frog aldoc (83% identical), zebrafish aldoca (79% identical), Drosophila melanogaster Ald1 (68% identical), Caenorhabditis elegans aldo-1 (64% identical), and 2 more. Paralogues in human: ALDOA (82% identical), ALDOB (70% identical).
Diseases named in the same sentence as ALDOC in open-access papers:
ALDOC is named in the same sentence as 57 diseases in open-access papers, as found by Europe PMC text mining. Sharing a sentence is not in itself a finding about the gene and the disease. The quoted sentences say what the papers report.
breast carcinoma (9 papers, 2021 to 2025). "For example, the downregulation of ALDOC expression inhibits glycolysis and proliferation in gallbladder cancer (GBC) cells, whereas reduced ALDOC expression weakens glycolysis and inhibits breast cancer growth." (PMID 40313939, 2025). "This suggested another potential breast cancer suppression mechanism via ALDOC activation in breast cancer cells exposed to CB agonists." (PMID 39527598, 2024). "Meta-analysis revealed that ALDOC expression was downregulated in all breast cancer subtypes, and the higher ALDOC expression was also associated with the higher survival of breast cancer patients." (PMID 39527598, 2024). "In breast cancer, ALDOC can be regulated by Let-7f and contributes to type II diabetes-mediated breast cancer." (PMID 35008539, 2021). "Similarly, ALDOC also mediate the glycolysis-related tumor progression of breast cancer and negatively coordinates with poor prognosis of patients." (PMID 40518543, 2025). "In breast cancer, high expression of ALDOC directly enhances glycolysis levels in tumor cells." (PMID 40535800, 2025). "ALDOC expression was pointedly higher in ER-ve and PR-ve breast cancer individuals." (PMID 38173442, 2024). "Similarly, previous study had showed that ALDOC overexpression was negatively correlated with aggressiveness of breast cancer." (PMID 39527598, 2024). "However, more studies are needed to verify the underlying mechanism for breast cancer suppression upon CB agonist exposure as well as the roles of ALDOC and its association with ECS in breast cancer progression." (PMID 39527598, 2024). "Since ALDOC downregulation was shown in all breast cancer subtypes, our results demonstrated the potential negative effect of CB agonist exposure on breast cancer via ALDOC induction." (PMID 39527598, 2024). "In this regard, in our study, we demonstrate that the combined knockdown of ALDOC and ENO2 significantly reduced lactate production and consequently attenuated the sphere-forming ability of both LUAD and breast cancer cell lines both in nutrient-rich and nutrient-restricted conditions." (PMID 36945054, 2023).
glioblastoma (9 papers, 2019 to 2024). The most malignant astrocytic tumor (WHO grade IV). "Under hypoxia, HIF1a binds to the hypoxia- responsive element (HRE) on the promoter region of ALDOC, thus causing metabolic reprogramming or aberration of glycolysis to promote glioblastoma and ovarian cancer." (PMID 36945054, 2023). "Similar to ALDOC in glioblastomas, our results showed a significantly inverse correlation between ALDOC and IDH1 mutation status in TCGA glioma cohort (TCGA_GBMLGG, n = 1119)." (PMID 31450822, 2019). "Furthermore, ALDOC was also associated with significantly increased survival time in glioblastoma patients, implying a tumor-suppressor factor in glioblastomas." (PMID 31450822, 2019). "From our results, higher ALDOC mRNA expression in proneural subtype than in mesenchymal subtype of glioblastomas might imply the interaction of ALDOC with various oncogenic mutations, and possibly influence overall survival time." (PMID 31450822, 2019). "Besides, the expression level of ALDOC was associated with molecular subtypes of glioblastomas and recurrent status in several data sets." (PMID 31450822, 2019). "Our results support high ALDOC expression in glioblastomas that might imply the mutated status of IDH1, less possibility of mesenchymal subtype, and predict a favorable prognosis." (PMID 31450822, 2019). "In addition, our results also show that the expression of ALDOC was associated with IDH1 genomic alteration event in glioblastomas." (PMID 31450822, 2019). "High level of ALDOC was found to correlate with the improved patient survival and reduced cancer progression in glioblastoma." (PMID 39527598, 2024). "In contrast to these findings, ALDOC is positively correlated with longer survival and good prognosis of glioblastoma patients and can inhibit cell migration and invasion in glioblastoma and additional cancer types." (PMID 33274599, 2021). "In this study, we screened microarray chips and TCGA data and found that ALDOC was lower expressed in mesenchymal subtype of glioblastomas." (PMID 31450822, 2019). "The data from the PRECOG database showed negative regulating of ALDOC expression in brain-related cancer, including astrocytoma, glioblastoma, glioma, medullobalstoma, meningioma, and neuroblastoma." (PMID 31450822, 2019). "We also proved that higher ALDOC expression in proneural subtypes than in mesenchymal type of glioblastomas was identified from the GSE54077 data set." (PMID 31450822, 2019). "We also observed a consistent trend with the glioblastoma cohort, namely, a low level of ALDOC expression in the unmethylated MGMT and IDH1 wild-type group (p < 0.0001, p < 0.0001, respectively)." (PMID 31450822, 2019). "After that, we also performed immunohistochemical stain (IHC) analysis to evaluate protein expression levels of ALDOC in glioblastoma tissues." (PMID 31450822, 2019). "In addition, compared to low-grade glioma, ALDOC expression was significantly downregulated in high-grade glioblastoma." (PMID 31450822, 2019). "The analysis of TCGA data revealed that ALDOC enriched in proneural subgroup of glioblastomas." (PMID 31450822, 2019). "In the future, although the detailed mechanism is still unclear, ALDOC might be viewed as a potentially proper target to predict tumor behavior and patient prognosis in glioblastomas." (PMID 31450822, 2019). "Nevertheless, the effect of the impairment of these isoforms on glycolysis is not clear since the downregulation of ALDOC produces contradictory effects on cell proliferation and migration in glioblastoma cells and in vivo." (PMID 36914921, 2023). "However, MGH57 (grade IV glioblastoma) revealed a relatively small subpopulation of malignant cells that do not express OLIG1, OLIG2, DLL1, CCND1, and IGFBPL1, but express ALDOC and ATP1A2." (PMID 33607293, 2021). "GSE4290 showed significant suppression of ALDOC in glioblastoma patients with non-tumor or low-grade groups." (PMID 31450822, 2019).
glioblastoma (continued). "Unlike ALDOA and ALDOB, we observed that ALDOC inversely correlated with histology stages through heat map analysis of TCGA glioblastoma cohort (p < 0.0001, n = 538)." (PMID 31450822, 2019). "Furthermore, we also proved that ALDOC mRNA and protein expression inversely correlated with non-mutated IDH1 expressions in glioblastoma patient cohorts." (PMID 31450822, 2019). "Our analysis revealed a significant decrease in ALDOC expression was found in patients with WHO stage II and III low-grade glioma (LGG) as well as WHO stage IV glioblastoma (GBM) compared with nontumor samples." (PMID 38741139, 2024).
glioma (9 papers, 2018 to 2024). A benign or malignant brain and spinal cord tumor that arises from glial cells (astrocytes, oligodendrocytes, ependymal cells). "The pancancer profile also demonstrated lower ALDOC expression levels in brain tumors, such as gliomas, medulloblastomas, and meningiomas, than in other cancer types." (PMID 38741139, 2024). "Both low-grade gliomas and GBM, with wild-type and mutated IDH1, showed correlations with various clinicopathological events, and the difference in ALDOC expression was statistically significant on its own." (PMID 38741139, 2024). "ALDOC was however expressed in a sporadic and infrequent pattern; very few cells in the EM gliomas expressed PCDH15 and VCAN." (PMID 37055795, 2023). "ALDOC, an astrocyte-specific marker in all regions of the brain, is linked to various gliomas, but its presence in medulloblastoma has not been reported." (PMID 38350915, 2024). "In addition, compared with control (normal brain tissue, n = 8), a little lower ALDOC expression was detected in glioma patients (n = 276)." (PMID 31450822, 2019). "Through GSE4412 analysis, we found ALDOC expression in grade IV lower than grade III gliomas." (PMID 31450822, 2019). "Of all 64 glioma samples, low ALDOC expression level was observed in 37 (57.8%) cases." (PMID 31450822, 2019). "Besides, the expression of ALDOC is not only negatively associated with IDH1, but is also related to better prognosis in gliomas." (PMID 31450822, 2019). "Furthermore, our results also imply that ALDOC mRNA and protein expression are inversely correlated with non-mutated IDH1 expression and play a good prognostic role in gliomas." (PMID 31450822, 2019). "Additionally, we also recruited another clinical cohort, CGGA (Chinese Glioma Genome Atlas), and found the consistent trend that expression level of ALDOC correlated with survival curve in clinical patients." (PMID 31450822, 2019). "To examine the role of ALDOC or PPARγ signaling in GBM clinical cohorts, we assessed additional clinical data from the TCGA glioma dataset." (PMID 38741139, 2024). "Consistent with the changes in expression, patients with higher expression of LDHA, MIF, NAMPT, PGK1, SAT1, and PLOD2, and lower expression of ALDOC, ABAT, ADCY2, GALNT13, and PDE8B showed poorer survival rates in all glioma samples." (PMID 38989284, 2024). "Regarding the primary-recurrent-secondary (PRS) type, ALDOC and ABAT exhibited decreased expression, while MIF and PGK1 showed increased expression in recurrent and secondary glioma groups." (PMID 38989284, 2024). "To examine the role of ALDOC or PPARγ signaling in GBM clinical cohorts, we examined additional clinical events recorded in the TCGA glioma dataset." (PMID 38741139, 2024). "Similar to the TCGA datasets, all 11 genes exhibited WHO grade-dependent expression in glioma samples, with 6 upregulated (LDHA, MIF, NAMPT, PGK1, SAT1, and PLOD2) and 5 downregulated genes (ALDOC, ABAT, ADCY2, GALNT13, and PDE8B)." (PMID 38989284, 2024). "On the other hand, aldolase C (ALDOC) and cytochrome oxidase subunit 7A2 (COX7A2), which were both negatively co-expressed genes of COL5A1, were good prognostic factors of gliomas." (PMID 34868960, 2021). "Furthermore, ALDOC might be the prognostic factor in high-grade gliomas." (PMID 31450822, 2019).
gallbladder cancer (8 papers, 2021 to 2025). "In gallbladder cancer, disrupting ALDOC protein stability leads to loss of the ability to sense glucose levels inside and outside the cell, thereby activating the AMPK pathway, enhancing tumor glycolysis, and promoting malignant proliferation 25 as well as metastasis 26 of the tumor." (PMID 40535800, 2025). "In gallbladder cancer, ALDOC knockdown significantly downregulated glucose uptake, glycolysis, and cell proliferation." (PMID 38739943, 2024). "Meanwhile, ALDOC was overexpressed in gallbladder carcinoma, melanoma, and lung cancer, associated with their growth or pathogenesis." (PMID 34777463, 2021). "For instance, ALDOC has been elucidated upregulated in gallbladder carcinoma (GBC) and reported to promote the growth of GBC by binding with MUC16 C-terminal." (PMID 34456184, 2021). "Moreover, simple ALDOC knockdown is able to significantly inhibit glucose uptake and glycolysis of gallbladder cancer cells." (PMID 40518543, 2025).
melanoma (7 papers, 2014 to 2024). A malignant, usually aggressive tumor composed of atypical, neoplastic melanocytes. "In the third melanoma variant, ALDOC overexpression augmented certain characteristics of malignancy and reduced others." (PMID 33274599, 2021). "The present study using brain‐metastasizing variants from three human melanomas explores the functional role of ALDOC in the formation and maintenance of melanoma brain metastasis (MBM)." (PMID 33274599, 2021). "Assaying the functional consequences of upregulating ALDOC expression on parameters of tumor progression, we discovered that the three melanoma variants responded differently to alterations in ALDOC expression." (PMID 33274599, 2021). "ALDOC overexpression promoted the proliferation of these three melanoma variants when grown in the presence of microglia‐derived factors." (PMID 33274599, 2021). "Along this line, microglia cells were shown to upregulate the expression of ALDOC in brain-metastasizing melanoma cells, thereby facilitating brain metastasis formation." (PMID 38215076, 2024). "ALDOC overexpressing YDFR.CB3 and DP.CB2 melanoma cells were compared to the corresponding control cells expressing endogenous ALDOC levels." (PMID 33274599, 2021). "The response of melanoma cells from 2 different patients to ALDOC upregulation was diametrically divergent." (PMID 33274599, 2021). "We therefore examined the effect of ALDOC overexpression or downregulation on melanoma cell viability." (PMID 33274599, 2021). "The finding that ALDOC plays a tumor‐promoting function in certain melanomas should be taken into consideration when planning therapy trials involving targeting of glycolysis pathways or when ALDOC itself is targeted." (PMID 33274599, 2021). "The melanoma‐microglia cross‐talk upregulates the expression of aldolase C (ALDOC) in melanoma cells from several patients." (PMID 33274599, 2021). "Previous studies indicated that microglia cells upregulate the expression of aldolase C (ALDOC) in melanoma cells." (PMID 33274599, 2021). "ALDOC overexpression slightly increased melanoma viability in M12.CB3 cells, only after a 24‐h cultivation." (PMID 33274599, 2021). "This was done by overexpressing ALDOC in melanoma cells and evaluating molecular and functional malignancy parameters of these cells." (PMID 33274599, 2021). "The glycolytic enzyme aldolase C (ALDOC) whose expression in melanoma cells was upregulated by microglia reshapes the malignant phenotype of melanoma cells." (PMID 33274599, 2021). "Reverse‐phase protein array analysis was performed in ALDOC overexpressing or control MBM cell lines in order to identify proteins involved in ALDOC‐mediated regulation of melanoma malignancy phenotype." (PMID 33274599, 2021). "We next asked whether ALDOC overexpression would influence the capacity of melanoma cells to form spontaneous brain micrometastasis." (PMID 33274599, 2021). "We then asked whether ALDOC also functions in an opposite manner in vivo with respect to promoting or inhibiting the malignancy phenotype of melanoma cells." (PMID 33274599, 2021). "In order to examine whether ALDOC upregulation in melanoma cells facilitates melanoma penetration of the blood–brain barrier (BBB), we used a BBB model, which serves to simulate the extravasation of melanoma cells and their migration toward microglia." (PMID 33274599, 2021). "In sharp contrast, ALDOC overexpression in the second brain‐metastasizing melanoma variant reduced or did not affect the same malignancy features." (PMID 33274599, 2021). "In order to establish whether ALDOC regulates melanoma cell adhesion to BEC, we compared the adhesion of control and ALDOC overexpressing cells to BEC." (PMID 33274599, 2021). "We therefore asked whether ALDOC upregulation further contributes to melanoma viability in the presence of microglia‐derived soluble factors." (PMID 33274599, 2021).
melanoma (continued). "It would be interesting to explore in future studies whether and how ALDOB and ALDOC are involved in melanoma cell invasion and survival." (PMID 24959248, 2014). "ALDOC could directly activated transcription of the gene in melanoma cells." (PMID 34456184, 2021). "As ALDOC interacts with cytoskeletal proteins (e.g., F‐actin, tubulin) and alters the migratory capacity of tumor cells, we examined whether ALDOC overexpressing melanoma cells would manifest an altered ability to migrate through collagen‐coated transwells." (PMID 33274599, 2021). "Thus, ALDOC influences the migration of these two MBM variants in an opposite manner, demonstrating that the same type of tumor cells, derived from different individual melanoma patients, may be differentially influenced by the same microenvironmental cue." (PMID 33274599, 2021). "XTT assays demonstrated that ALDOC expression levels did not alter melanoma viability in either YDFR.CB3 or DP.CB2 ALDOC overexpressing cells or in cells expressing downregulated ALDOC levels (data is not shown)." (PMID 33274599, 2021). "ALDOC mRNA expression was higher in 3D spheroids co‐cultured with microglia cells, than in respective 3D spheroids of melanoma cells cultured without microglia." (PMID 33274599, 2021). "In melanoma, NME1 has been shown to inhibit metastasis by activating ALDOC transcription." (PMID 33737938, 2021).